MTOR (mechanistic target of rapamycin kinase)
Diseases named in the same sentence as MTOR in open-access papers (continued):
Sharing a sentence is not in itself a finding about the gene and the disease.
Cerebral ischemia (continued). "Finally, this study confirmed that epalrestat can regulate apoptosis and autophagy of brain microvascular endothelial cells after cerebral ischemia through AR/AKT/mTOR signal pathway." (PMID 36940077, 2023). "Multiple reports reveal cerebral ischemia induces AMPK phosphorylation inhibiting mTOR." (PMID 37691119, 2023). "A holistic view of mTOR and αKG-mediated interactions may contribute to finding more effective therapeutic strategies for cerebral ischemia." (PMID 37252190, 2023). "Excessive autophagy could exacerbate brain ischemia, and several research articles indicate that mTOR signaling exerts neuroprotective effects by inhibiting autophagy." (PMID 37631097, 2023). "Many studies on mTOR and cerebral ischemia have focused on autophagy, which plays a critical role in the maintenance of proteostasis and the survival of neurons by promoting the lysosome-driven removal of damaged or non-essential molecules and defective organelles (see Section 1.3)." (PMID 35269956, 2022). "Similarly, Ibrutinib also can ameliorate autophagy and cerebral ischemia/reperfusion injury through the PI3K/Akt/mTOR signal pathway." (PMID 36432062, 2022). "The AMPK/mTOR signaling pathway is known to regulate autophagy after cerebral ischemia." (PMID 36539418, 2022). "Similarly, dexmedetomidine upregulates autophagy in astrocytes by activating the TSC2/mTOR pathway and has a protective effect against cerebral ischemia." (PMID 36110390, 2022). "In summary, our results suggest that the neuroprotective mechanisms of ST2-104 peptide related to preventing apoptotic death following cerebral ischemia injury can be also attributed to inhibition of autophagy via control of a CaMKKβ/AMPK/mTOR signaling pathway." (PMID 34362425, 2021). "Furthermore, the mTOR signal pathway was reported to be highly dependent on the neuroprotective effect in cerebral ischemia." (PMID 35095491, 2021). "Existing studies reported that cerebral ischemia down-regulates mTOR as well as Akt, which could prevent BAD translocation in the mitochondrial membrane." (PMID 35095491, 2021). "Interestingly, i.n. application of Cr after cerebral ischemia averted the worsening imbalance between autophagy and mTOR signaling and reduced the infarct size in both wild-type and CrT-null mice." (PMID 34324436, 2021). "Therefore, the antiapoptotic effects of ST2-104 in the face of a cerebral ischemia injury likely involve the CaMKKβ/AMPK/mTOR pathway." (PMID 34362425, 2021). "Research reported that electroacupuncture might strengthen autophagy via mTOR signaling pathway, reducing the early impairment in cerebral ischemia rats." (PMID 34987374, 2021). "Collectively, the outcome of neuronal survival with the modification of mTOR pathway in cerebral ischemia–reperfusion could depend on its net effects on neurons and the BBB." (PMID 34354602, 2021). "Our results demonstrated that DMS decreased the enhanced expression of p-mTOR and p70S6K activated by cerebral ischemia, which confirmed that S1P/SphK signaling could modulate the mTOR/p70S6K pathway during autophagy." (PMID 29186197, 2017). "In summary, this study proved that EA pretreatment at Baihui acupoint had a protective function on the brain by upregulation of autophagy during early cerebral ischemia, and its regulation of autophagy may depend on the mTOR signal pathway." (PMID 27547233, 2016). "The discoveries indicated two points: first, the brain cell autophagy that occurred during cerebral ischemia was mainly mTOR-dependent, and, second, EA pretreatment at Baihui acupoint may further regulate autophagic expression through the mTOR pathway." (PMID 27547233, 2016).
Cerebral ischemia (continued). "Given the neuroprotective role of the PI3K/Akt pathway, we hypothesized that the PI3K/Akt/mTOR pathway may be inactivated after cerebral ischemia injury." (PMID 25954164, 2015). "Moreover, we demonstrated that cerebral ischemia–reperfusion injury (CIRI) promoted mTOR/HIF‐1α signaling pathway expression, which could be further enhanced via the knockdown of SESN2." (PMID 40032632, 2025). "Gabapentin dose-dependently reduced neuronal injury induced by cerebral ischemia-reperfusion preventing the oxidative stress-related autophagy via the activation of the phosphoinositide 3 kinase (PI3K)/Akt/mammalian (or mechanistic) target of rapamycin (mTOR) (PI3K/Akt/mTOR) pathway." (PMID 38776036, 2024). "Moreover, the Akt/mTOR is a key regulatory pathway of apoptosis, and its activation can upregulate Bcl-2 expression, reduce the ratio of Bcl-2/Bax, and minimize the apoptosis of nerve cells after repeated cerebral ischemia–reperfusion." (PMID 35669881, 2022). "The detailed mechanism of the protective effects of simple O-substituted isoflavones against cerebral ischemia reperfusion might be related to the PI3K/AKT/ERK/mTOR or GSK-3β pathway, eNOS/Keap1/Nrf-2/HO-1 pathway, TLRs/TIRAP/MyD88/NFκ-B pathway, and Bcl-2-regulated anti-apoptotic pathway." (PMID 36142301, 2022). "Thus, it was postulated that NGF could affect the neurological function resulting from cerebral ischemia by modulating Akt/mTOR to mediate apoptotic and autophagic activities after CIR, in the form of mature NGF and proNGF." (PMID 35391929, 2022). "In addition, other pleiotropic metformin actions may also function in cerebral ischemia, such as suppressing mTOR, by which AMPK controls autophagy, cell growth, and secondary inflammation." (PMID 28634570, 2017). "For example, search terms included “stroke OR cerebral ischemia AND RhoA/ROCK”, “MSC OR EVs OR secretome AND stroke”, and “mTOR AND stroke OR cerebral ischemia AND treatment”." (PMID 38666949, 2024). "Inhibiting PTEN expression to reactivate mTOR pathway can promote significant sprouting, regeneration and functional recovery of optic nerve axons and CST axons after cerebral ischemia." (PMID 37426810, 2023). "For instance, resveratrol has a neuroprotective effect against cerebral ischemia/reperfusion injury by up-regulating the expression of p-JAK2, p-STAT3, p-AKT, p-mTOR, and Bcl2, and down-regulating the expression of cleaved caspase-3 and Bax." (PMID 36940077, 2023). "In this study, we confirmed that SIK2 could play a similar role to AMPK in the mTOR pathway, which promoted the phosphorylation expression of mTORC1 and the energy metabolism, induced the occurrence of mitochondrial autophagy, and improved the cerebral ischemia-reperfusion injury." (PMID 35586047, 2022). "Intriguingly, in a mouse brain ischemia model, inhibition of mTOR upstream suppressor PTEN observed that mTOR activation was directly involved in cortical neuron proliferation and enhanced neuronal axon densities." (PMID 36505409, 2022). "Ligustilide can upregulate the expression of p-pI3k, p-Akt, and p-mTOR proteins in the brain of rats with cerebral ischemia–reperfusion and show the activation of the PI3K/Akt/mTOR pathway." (PMID 35173614, 2021). "In this study, we investigated how Rapalink-1, a third-generation mTOR inhibitor, would affect neuronal survival and BBB disruption in the very early stage of cerebral ischemia–reperfusion that is within the time window of thrombolysis therapy." (PMID 34354602, 2021). "Some other researchers have found similar results indicating that cerebral ischemia induced the robust activation of JNK signaling and inhibition of PI3K-Akt-mTOR pathway activity." (PMID 29696512, 2018). "In cerebral ischemia, C2dat2 sequesters miR-30d-5p to activate DDIT4-dependent autophagy and apoptosis, potentiating reperfusion injury, while SNHG12 silencing amplifies mesenchymal stem cell efficacy by activating PI3K/AKT/mTOR signaling." (PMID 40777664, 2025).
Cerebral ischemia (continued). "Besides, research underscores schaftoside’s neuroprotective capacity against cerebral ischemia/reperfusion injury (CI/RI), both in vitro and in vivo, by modulating the autophagy-mediated AMPK/mTOR pathway." (PMID 39846000, 2024). "mTOR is a downstream molecule in the PI3K/AKT signaling pathway, and a previous study also found that activation of mTOR contributes to protection against cerebral ischemia-reperfusion injury." (PMID 36133785, 2022). "Besides, the AMPK can impair mTOR phosphorylation, reduce s757-ULK1 phosphorylation, promote s317-ULK1 phosphorylation, and induce autophagy in cerebral ischemia–reperfusion injury." (PMID 35669881, 2022). "Accumulating evidence has confirmed that, under the injuries of stroke, cerebral ischemia, and I/R and activation of PI3K/Akt or PI3K/Akt/mTOR signaling pathway, PIK3CA, PIK3R1, AKT1, MAPK1, MAPK3 are main genes that play important roles in promoting cell survival and reducing cellular apoptosis." (PMID 35432563, 2022). "In this study, we investigated whether Rapalink-1, a third-generation mTOR inhibitor, would inhibit both mTORC1 and mTORC2 and its effects on neuronal survival and BBB disruption in cerebral ischemia–reperfusion." (PMID 34354602, 2021). "Our results collectively revealed that ibrutinib could effectively ameliorate cerebral ischemia/reperfusion injury via ameliorating inflammatory response, oxidative stress, and improving autophagy through PI3K/Akt/mTOR signaling pathway in diabetic mice." (PMID 34605340, 2021). "During acute cerebral ischemia/reperfusion, RLIC leads to increased levels of p-mTOR and p-p70S6K in brain tissue, and fewer autophagosomes in CNS via the activation of mTOR/p70S6K pathway, thereby contributing to decreased neurological deficits and infarct size." (PMID 31130914, 2019). "This hypothesis is supported by previous studies showing that rapamycin provides neuroprotective effects against cerebral ischemia through the concomitant activation of autophagy and the PI3K/Akt-mTOR axis." (PMID 26325184, 2015). "Nevertheless, it is still unclear whether there is a negative feedback pathway from mTOR to Akt during cerebral ischemia/reperfusion (I/R)." (PMID 42284260, 2026). "Therefore, we hypothesized that epalrestat could inhibit the apoptosis and autophagy of BMVECs through the ATK/mTOR signaling pathway to maintain endothelial cell barrier function, and thus protect against BBB damage and further injury in cerebral ischemia." (PMID 36940077, 2023). "The classical autophagy regulatory pathway PI3K/AKT/mTOR can regulate neuronal autophagy, but whether it regulates astrocyte autophagy in cerebral ischemia has not been determined." (PMID 36110390, 2022). "EA at GV20, GV4, and ST36 decreases the level of mammalian target of rapamycin (mTOR) and increases the levels of autophagy-related protein Beclin1 and LC3, which can inhibit neuronal injury induced by autophagy during the reperfusion period of cerebral ischemia." (PMID 35241146, 2022). "Akt and mTOR overexpression improved the protective effects after cerebral ischemia-reperfusion injury in MCAO rats, suggesting that the activation of the PI3K/Akt/mTOR signaling pathway provides significant neuroprotective effects against cerebral ischemia-reperfusion injury." (PMID 34955724, 2021). "In summary, our finding collectively demonstrated that Ibrutinib could effectively ameliorate cerebral ischemia/reperfusion injury via ameliorating inflammatory response, oxidative stress, and improving autophagy through PI3K/Akt/mTOR signaling pathway in diabetic mice." (PMID 34605340, 2021). "Therefore, intermittent hypoxia can activate mTOR signal pathway to worsen cerebral injury by aggravating anoxia, ischemia and the release of inflammatory factors such as TNF-α in the central nervous system after cerebral ischemia." (PMID 28177899, 2017).
Cerebral ischemia (continued). "In summary, apart from mTOR, AMPK and NLRP3, other signals, such as Sphk1, DJ-1, LRRK2 could modulate autophagy to participate in microglia polarization as well as inflammatory mediators’ production, thus affecting neuroinflammatory processes in cerebral ischemia, AD, TBI and other CNS diseases." (PMID 37548945, 2024). "However, PNS administration dramatically raised the p-Akt/Akt, p-mTOR/mTOR, and p-p70S6K/p70S6K ratios in a dose-dependent manner, suggesting that Akt/mTOR/p70S6K pathway might participate in the protective mechanisms of PNS against cerebral ischemia injury." (PMID 35770087, 2022). "Furthermore, it has been shown that TrkB receptor gene expression varies between hippocampal subregions and that the response of mTOR to acute brain ischemia differs in hippocampal subfields, with endogenous downregulation of mTOR activity occurring in the CA3 but not the CA1 subfield." (PMID 35465399, 2022). "Thus our hypothesis was reached PI3K/Akt/mTOR and ERK1/2 pathways may provide distinct cellular targets for a new generation of therapeutic agents for the treatment of stroke, and TP and DAHP may be potential neuroprotective agents for cerebral ischemia/reperfusion injury." (PMID 25954164, 2015).
Hepatic steatosis (94 papers, 2013 to 2026). Steatosis is a term used to denote lipid accumulation within hepatocytes. "In the current study, CePA was verified to spatially block the phosphorylation and activation of mTOR to alleviate hepatic steatosis, lipid-associated damage, and fibrosis in MASH in vitro and in vivo." (PMID 39873005, 2024). "AKT1 deficiency led to the inhibition of AKT/mTOR/S6K signaling pathway in hepatocytes, which was crucial for the development of hepatic steatosis and provided a new scheme for the development of NAFLD therapy." (PMID 36866057, 2023). "Hence, we concluded that hepatic AGT deletion attenuated Western diet-induced liver steatosis and was associated with inhibition of Akt/mTOR/SREBP-1c signaling." (PMID 31604805, 2019). "Dysregulation of mTOR signaling has been implicated in fatty liver diseases." (PMID 31068812, 2019). "Furthermore, various previous studies suggested that deletion or pharmacological inhibition of IP6K ameliorates hepatic steatosis, which has been associated with reduced expression of markers of fatty acid uptake and lipogenesis as well as augmented Akt, mTOR and GSK3β signalling in the liver." (PMID 41032702, 2025). "In addition, network pharmacology and experiment study showed that this protective effect of KTZG from hepatic steatosis might be associated with its ability to regulate the AMPK/mTOR signaling pathway." (PMID 32884949, 2020). "Pharmacologic inhibition of mTOR by torin-1, a novel mTOR inhibitor, could reverse the inhibition of TFEB, liver steatosis, and liver injury in chronic-plus-binge alcohol treatment, suggesting a potential association between the mTOR pathway and TFEB inhibition by alcohol." (PMID 31614437, 2019). "Parallel studies have established that AKT/mTOR signaling exerts dual regulatory effects in liver steatosis management promoting oxidative stress resolution while enhancing autophagic flux." (PMID 41411370, 2025). "Its underlying mechanism involves inhibiting oxidative stress and inflammation through the AMPK/mTOR pathway and regulating the number of locally generated lymphatic vessels, thereby exerting a therapeutic effect on fatty liver." (PMID 41225688, 2025). "In the present study, we suspected that the AMPK/mTOR and PPARα pathways are involved in L-Phe-induced liver steatosis." (PMID 40588730, 2025). "This study is to explore the molecular mechanisms underlying the potential crosstalk between Wnt/β-catenin and mTOR signaling in hepatic steatosis." (PMID 38152126, 2023). "Conversely, the phosphorylation level of mTOR, which plays a role in hepatic steatosis, was suppressed." (PMID 36982617, 2023). "An SGLT inhibitor can activate AMPK phosphorylation and inhibit the mammalian target of rapamycin (mTOR) phosphorylation, thereby improving hepatic steatosis." (PMID 37063264, 2023). "Accordingly, peroxisomal β-oxidation is a major source of acetyl-CoA that regulates the mTOR-autophagy axis, leading to the promotion of hepatic steatosis." (PMID 37670786, 2023). "Betaine is an antioxidant that inhibits inflammation and apoptosis but upregulates cytoprotective Akt/mTOR signaling in fatty liver disease." (PMID 36803569, 2023). "Previous studies showed that the formation of fatty liver in geese by overfeeding was accompanied by the activation of the PI3K-Akt-MTOR pathway, suggesting that the PI3K-Akt-MTOR pathway played a key role in regulating the lipid metabolism." (PMID 36204629, 2022). "The knockout of LRP6, a receptor for canonical Wnt ligands, was shown to significantly induce liver steatosis through active hepatic AKT/PI3K/mTOR." (PMID 35800214, 2022). "Hyperinsulinemia can also upregulate hepatic lipogenesis via the insulin-Akt-mTOR signaling pathway, which can contribute to hepatic steatosis and a further decrease in insulin clearance." (PMID 34948019, 2021). "Accordingly, liver-specific PPDPF overexpression effectively inhibits HFD-induced mTOR signaling activation and hepatic steatosis in mice." (PMID 34031390, 2021).